PVT1 (Pvt1 oncogene)
Diseases named in the same sentence as PVT1 in open-access papers (continued):
Sharing a sentence is not in itself a finding about the gene and the disease.
gastric cancer (continued). "Particularly, in gastric cancer, overexpressed lncRNAs such as LINC00673, LincRNAFEZF1-AS1, PVT1 and ANRIL were found to be indicators for poor prognosis." (PMID 30560474, 2019). "PVT1 directly binds to FOXM1 protein to increase its stability, enhancing gastric cancer cell proliferation and invasion." (PMID 29970131, 2018). "Our previous studies have revealed that the expression pattern of several lncRNAs, such as HOTAIR, SPRY4-IT1, BANCR, and PVT1, is altered in human NSCLC and gastric cancer." (PMID 27713133, 2017). "The top 4 predicted gastric cancer-related lncRNAs, H19, HOTAIR, MEG3, and PVT1 were confirmed by the updates of the LncRNADisease database." (PMID 28963512, 2017). "Accumulating evidence suggests that PVT1 is over-expressed in many types of human cancers, including ovarian cancer, breast cancer, HCC, bladder cancer and gastric cancer." (PMID 29137343, 2017). "In addition, PVT1 could regulate gastric cancer cell growth both in vitro and in vivo." (PMID 25890171, 2015). "However, the function role and molecular mechanism of PVT1 in gastric cancer remains unclear." (PMID 25890171, 2015). "Moreover, PVT1 could regulate gastric cancer cells proliferation both in vitro and in vivo." (PMID 25890171, 2015). "For example, lncRNA PVT1 promotes angiogenesis by stabilizing STAT3, which then activates the STAT3/VEGFA signaling axis that drives upregulation of VEGF expression and tumor progression in gastric cancer—this is likely relevant to other cancers as well." (PMID 41154428, 2025). "For instance, PCAT1, PVT1, and PCAT19 in prostate cancer, CUPID1 and CUPID2 in breast cancer, PTCSC2 and PTCSC3 in thyroid cancer, LINC00673 in pancreatic cancer, lncPSCA in gastric cancer, as well as LCETRL3 and LCETRL4 in non-small cell lung cancer, are implicated in malignant development." (PMID 37072811, 2023). "In gastric cancer, STAT3 occupies the promoter of PVT1 and stimulates PVT1 expression." (PMID 36295083, 2022). "PVT1 could increase the expression of CD151 through binding to miR-152 and inhibiting the expression of miR-152 to promote gastric cancer." (PMID 34222025, 2021). "Moreover, Circular RNA circ-PVT1 upregulated ZEB1 expression by sponging miR-124-3p and enhanced paclitaxel resistance of gastric tumor and gastric cancer cells." (PMID 33482814, 2021). "In addition, lncRNAs PVT1, HOTAIR and CASC9 also promoted PTX resistance of gastric cancer through modulating expression of various genes." (PMID 32192494, 2020). "The pro-angiogenic function of PVT1 is also exerted through direct interaction with phospho-STAT3, leading to protein stabilization and activation of the downstream pathway, resulting in VEGFA upregulation in gastric cancer." (PMID 32228602, 2020). "Located at the 8q24 chromosomal region, the long nonprotein-coding gene PVT1 has been shown to be overexpressed in various cancers including PCa, breast, pancreatic, lung, and gastric cancers." (PMID 31766781, 2019). "PVT1 could interact with FOXM1 directly and increase its protein expression in gastric cancer and increased glucose uptake, lactate production, and the expression of HK2 in osteosarcoma cancer." (PMID 30083911, 2019). "PVT1 directly binds to FOXM1 and enhances its stability, and FOXM1 in turn initiates PVT1 expression through binding to the PVT1 promoter, thus forming a feedback loop between PVT1 and FOXM1 that plays a critical role in promoting gastric cancer cell proliferation and invasion." (PMID 31497532, 2019). "Second, PVT1 could also alter the expression of certain genes, including bind to EZH2 in non-small cell lung cancer and gastric cancer." (PMID 30083911, 2019). "To explore the effects of PVT1 on GC, we stably overexpressed and stably silenced PVT1 expression in SGC-7901 cells and observed the influence of PVT1 on the tumorigenicity of gastric cancer cells in a mouse model." (PMID 31205469, 2019).
gastric cancer (continued). "The expression of PVT1 was increased in gastric cancer tissues compared with adjacent non-neoplastic tissues, it up-regulation was associated with lymph node metastasis and tumor-node-metastasis (TNM) stage." (PMID 29108264, 2017). "In gastric cancer, FOXM1 can bind to the promoter region of PVT1 and enhance its transcription." (PMID 29244840, 2017). "In our present study, we demonstrated that PVT1 expression was markedly increased in gastric cancer tissues compared with corresponding non-tumor tissues." (PMID 25890171, 2015). "Taken together, these results demonstrated that PVT1 expression was an independent prognostic indicator for DFS (HR = 2.216, 95% CI: 1.130-4.345, p = 0.021) and OS (HR = 2.092, 95% CI: 1.068-4.096, p = 0.031) in patients with gastric cancer." (PMID 25890171, 2015). "A Kaplan-Meier analysis has shown that therapy without 5-FU significantly improves the first progression survival and OS of gastric cancer patients with high PVT1 expression, while these patients do not experience survival-related benefits from 5-FU-based chemotherapy." (PMID 32460771, 2020). "Likewise, AGS, MKN45, SGC7901, and BGC823 gastric cancer cell lines have higher PVT1 expression compared to GES1 normal gastric epithelium cell line." (PMID 32083000, 2020). "PVT1 was found upregulated using quantitative RT-PCR in colorectal cancer patients refractory to 5-fluorouracil (5-FU) in neoadyuvancy (primary resistance), and also in colorectal and gastric cancer patients receiving but not benefiting from cisplatin." (PMID 32083000, 2020). "PVT1 expression was significantly elevated in drug-resistant cell lines in gastric cancer, colorectal cancer, and osteosarcoma compared to non-resistant cell lines, and all three cancer types expressed higher levels of PVT1 compared to matched non-cancerous tissues." (PMID 31249809, 2019). "Importantly, circ-PVT1 could bind to miR-124-3p as a miRNA sponge to up-regulate ZEB1 expression, thereby expediting paclitaxel resistance of gastric cancer cells." (PMID 31793989, 2019). "Furthermore, in gastric cancer, there is a lack of consensus between increased PVT1 expression and lymph node metastasis." (PMID 31249809, 2019). "Indeed, PVT1 bound miR-186 and induced upregulation of HIF-1α (Hypoxia-inducible factor 1-alpha subunit), a target of miR-186 which was related to poor prognosis and invasiveness in gastric cancer." (PMID 29147648, 2017). "Many studies have suggested using the levels of PVT1 expression to predict lymph node metastasis in gastric cancer, histological grade and lymph node metastasis in non-small cell lung cancer, clinical stage and N-classification in pancreatic cancer, and the recurrence rate in HCC." (PMID 29348896, 2017). "In gastric cancer (GC), different lncRNAs are related to drug resistance, by modulating the expression of drug resistance-related genes, such as the oncogenic lncRNAs MACC1-AS1, PVT1 and HAGLR, which are upregulated and promote 5-FU resistance in GC cells." (PMID 36866275, 2023). "In gastric cancer cells, PVT1 was demonstrated to upregulate HIF-1α expression by sponging miR-186 to revert miR-186-mediated repression of HIF-1α expression and consequentially promote GC cell progression indirectly." (PMID 28789687, 2017). "Although the 10q26.1-amplified gastric cancer cell line SNU16 expresses PVT1-PPAPDC1A20, PPAPDC1A fusion events have not been reported recurrent in human gastric cancers." (PMID 30361512, 2018).
breast cancer (141 papers, 2010 to 2026). A primary or metastatic malignant neoplasm involving the breast. "For example, the overexpression of PVT1 has been implicated in various forms of cancer, including acute myeloid leukemia, Hodgkin lymphoma, breast cancer—particularly TNBC—and ovarian cancer." (PMID 40149989, 2025). "DANCR and PVT1 are other lncRNAs implicated in promoting breast cancer cell proliferation through specific signaling pathways." (PMID 39912983, 2025). "In breast cancer, there has been documentation of several fusions involving the PVT1 lncRNA (plasmacytoma variant translocation 1), which resides in a fragile site on chromosome 8 and is implicated in a variety of cancers." (PMID 38473871, 2024). "The plasmacytoma variant translocation 1 (PVT1) lncRNA upregulated in breast cancer (BC) has been proposed to act as an oncogene through binding miR-128-3p and UPF1 and promoting EMT and, thus, proliferation and metastasis." (PMID 36766761, 2023). "Some studies were carried out to investigate the influence of the expression of plasmacytoma variant translocation 1 (PVT1) on prognosis and its clinical significance in patients with breast cancer, while the results were contradictory and uncertain." (PMID 33663093, 2021). "Although studies have shown that PVT1 splice variants are also overexpressed in breast cancer, and play a role in cancer progression, the underlying mechanisms by which these transcripts promote tumorigenicity is yet to be elucidated." (PMID 33801373, 2021). "PVT1 is a long non-coding RNA transcribed from a gene located at the 8q24 chromosomal region that has been implicated in multiple cancers including breast cancer (BC)." (PMID 33801373, 2021). "The PVT1 gene, according to previous research, encodes an oncogenic long non-coding RNA (lncRNA) that aids breast cancer cell growth in vivo." (PMID 35011637, 2021). "PVT1 amplification is associated with many clinicopathological characteristics in breast cancer, including regulation of apoptosis, EMT and metastasis." (PMID 33801373, 2021). "Contrastingly, a study has found that silencing the PVT1 promoter results in increased cell proliferation and competition in breast cancer cells, which was associated with an increase in MYC expression." (PMID 33499210, 2021). "PVT1 is a long noncoding RNA that is commonly overexpressed in breast cancer and has been implicated in the regulation of MYC oncogene, while JAK2 is a tyrosine kinase activating cancer-driving JAK/STAT signaling pathway." (PMID 34439480, 2021). "In this study, we report that the plasmacytoma variant translocation 1 (PVT1) lncRNA is involved in breast cancer progression." (PMID 34922601, 2021). "Several studies implicated PVT1 in aspects of cancer pathophysiology including the observations that rearrangement of the 8q24 region encoding MYC and PVT1 is frequently involved in human prostate, ovarian, and breast cancer." (PMID 33670447, 2021). "A recent meta‐analysis concluded that increased PVT1 expression was associated with lower overall survival in a wide variety of solid tumours, including breast cancer." (PMID 32058674, 2020). "High-level amplification and/or overexpression of PVT1 is associated with an invasive phenotype of breast cancer and reduced survival time in ovarian cancer patients." (PMID 32992461, 2020). "PVT1 was mechanistically linked to a common loci of breast cancer risk through its role as an apoptotic inhibitor." (PMID 31379598, 2019). "Chromosome conformation capture (3C)-based studies have identified higher-order chromatin structures connecting MYC and PVT1 to the breast cancer-associated 8q24 gene desert region." (PMID 30526553, 2018). "In another report, it has been mentioned that the apoptosis of breast cancer cells can be inhibited by plasmacytoma variant translocation 1 gene (PVT1)." (PMID 30386629, 2018).
breast cancer (continued). "Pvt1 encodes a long non-coding RNA that stabilizes Myc protein expression, and low copy number gains in Myc and Pvt1 cooperate to promote breast cancer development in mouse models." (PMID 28430642, 2017). "Similar results—the “loss” of miR-200 family mediated crosstalks between PVT1-mRNAs have also been proposed in breast cancer." (PMID 27966444, 2016). "Amplification of PVT1 is one of the most frequent events in a variety of malignant diseases, including colorectal cancer, serous ovarian and breast cancers, and has been associated with reduced survival duration in patients." (PMID 25890171, 2015). "Amplification of MYC/PVT1 has been shown to contribute to the pathogenesis of ovarian and breast cancer, and is part of the chromosome 8q24 prostate cancer risk locus." (PMID 22661320, 2012). "Coamplification of MYC and PVT1 seem to correlate with rapidly growing and progressive breast cancer and has been associated with poor outcome in postmenopausal or ERBB2-positive BC patients." (PMID 20932292, 2010). "Interestingly, PVT1 has been implicated in cancer and overexpression of mir-1204 is associated with tumour cell proliferation in breast cancer." (PMID 41421967, 2025). "For instance, lncRNA PVT1 has been implicated in gemcitabine resistance in breast cancer by upregulating drug efflux transporters and autophagy-related genes, thereby decreasing intracellular gemcitabine accumulation and enabling cancer cells to evade gemcitabine-induced apoptosis." (PMID 40723396, 2025). "Similarly to MYC, high expression levels of PVT1 have been associated with a poor prognosis in breast cancer and other human malignancies." (PMID 36901971, 2023). "The study will provide updated evidence to evaluate whether the expression of PVT1 is in association with poor prognosis in patients with breast cancer." (PMID 33663093, 2021). "Moreover, PVT1 expression is significantly linked to patient survival in those with colorectal, lung, and breast cancer." (PMID 31320749, 2020). "Aberrations of PVT1 are associated with different malignancies including cervical cancer, bladder cancer, colorectal cancer, gastric cancer, breast cancer, hepatocellular carcinoma, lung cancer, and breast cancer." (PMID 32358016, 2020). "However, the “promoter–enhancer competition” between PVT1 and MYC is currently only observed in breast cancer cell lines and mutation of the PVT1 promoter is only observed in breast cancer and malignant lymphoma." (PMID 31309249, 2019). "It was speculated that downregulation of PVT1 decreased the breast cancer aggressiveness and induced the risk of second malignancies." (PMID 28938549, 2017). "The lncRNA plasmacytoma variant translocation 1 (PVT1) is well known for its critical roles in carcinogenesis and progression of many cancers, including hepatocellular carcinoma, lung cancer, and breast cancer." (PMID 28265576, 2017). "For example, plasmacytoma variant translocation 1 gene (PVT1) could inhibit the apoptosis of breast cancer cells." (PMID 28658310, 2017). "In breast cancer, the overexpression of the plasmacytoma variant translocation 1 gene (PVT1) could inhibit the apoptosis of tumor cells, which is involved in the pathophysiology of breast cancer." (PMID 27672656, 2016). "A study modeling Myc/Pvt1 co-amplification in murine breast cancer initially proposed that increased Pvt1 expression promotes Myc protein stability through a post-translational mechanism." (PMID 40743223, 2025). "The lncRNA gene PVT1 has also been shown to actively regulate drug export and modulate autophagy, accounting for its upregulation in gemcitabine-resistant breast cancer cells." (PMID 40723396, 2025). "For instance, the lncRNAs PVT1 and GHET1 have been implicated in gemcitabine resistance in breast cancer via the upregulation of cellular nucleoside exporters and autophagy modulation." (PMID 40723396, 2025).
breast cancer (continued). "We found the breast cancer cell line SKBR-3 to have such a rearrangement, with a loss of exons 7, 8, and 9 of PVT1." (PMID 40027648, 2025). "Initial work supported the proposed oncogenic function of PVT1 in a murine model of breast cancer where genetically engineered Myc-Pvt1 co-amplification was observed to be more tumorigenic than Myc amplification alone." (PMID 39195572, 2024). "For example, the |log2 fold change| of lncRNA LINC00472, H19 and PVT1 are all less than 2, but there are still studies showing that they are related to breast cancer." (PMID 38978021, 2024). "The transcription factor SOX2 enhances the transcription of PVT1 by combining with the promoter of PVT1, and the upregulated PVT1 promotes the proliferation and invasion of breast cancer cells via EMT." (PMID 38978021, 2024). "A recent study highlighted the regulatory role of lncRNA PVT1 in the proliferation, invasion, and tumor growth of breast cancer cells in an orthotopic xenograft model." (PMID 39553554, 2024). "The PVT1 oncogene (PVT1) was among the genes amplified in breast cancer cells related to mitochondria-regulated nuclear gene expression helps breast cancer cells survive and proliferate." (PMID 36831498, 2023). "We consider the possibility of PVT1 promoting cell proliferation and metastasis by regulating the aerobic glucose metabolism in breast cancer cells through sponging the miR-145-5p." (PMID 36941464, 2023). "Another example of a cancer-relevant lncRNA is PVT1, known to be involved in cancer, which is significantly upregulated in breast cancer cell lines and promotes breast cancer cell proliferation and metastasis, through binding to mir-128-3p and UPF1." (PMID 37624034, 2023). "MALAT1 in myeloma and PVT1 in breast cancer promoted NRF2 protein stability by inhibiting Keap1 binding to NRF2." (PMID 36831498, 2023). "We consider PVT1 promoting cell proliferation and metastasis by regulating the aerobic glucose metabolism in breast cancer cells through sponging miR-145-5p." (PMID 36941464, 2023). "Our study found that PVT1 is highly expressed in breast cancer and is closely related to the patient’s lymph node metastasis." (PMID 36941464, 2023). "We first identified that changing the expression level of PVT1 in breast cancer cells can change the level of glycolysis of the tumor cells, thereby promoting the biological behavior of the tumor." (PMID 36941464, 2023). "We analyzed the expression of PVT1 and its correlation with the breast cancer related clinical data in the The Cancer Genome Atlas (TCGA) database." (PMID 36941464, 2023). "PVT1 was up-regulated in breast cancer tissues and was positively correlated with the clinical stage of breast cancer patients." (PMID 36941464, 2023). "Taken together, these findings showed that PVT1 promoted breast cancer cell proliferation and growth in vivo." (PMID 36941464, 2023). "Our metabolism experimental data also showed that overexpression of PVT1 can enhance breast cancer cells glycolysis." (PMID 36941464, 2023). "To elucidate the molecular mechanisms underlying the effects of PVT1 on breast cancer cells, we performed RNA-seq and examined the mRNA expression profiles after overexpressing PVT1 in breast cancer cell line MDA-MB-231." (PMID 36941464, 2023). "PVT1 regulates glycolysis related genes expression by competitively binding to endogenous miR-145-5p in breast cancer cells to change the metabolic phenotype." (PMID 36941464, 2023). "The data indicate that lncRNA PTV1 is upregulated in breast cancer cells and tissues and that knocking down lncRNA PVT1 inhibits the migration and proliferation of breast cancer cells and induces apoptosis." (PMID 36379920, 2022). "The effect of PVT1 on breast cancer progression suggests that PVT1 has potential use in antitumor therapies and deserves further investigation." (PMID 34922601, 2021).